JUN (Jun proto-oncogene, AP-1 transcription factor subunit)
Diseases named in the same sentence as JUN in open-access papers (continued):
Sharing a sentence is not in itself a finding about the gene and the disease.
tumor (continued). "In the TCGA-HCC dataset, 13 genes were identified with significant correlation with SAMD13 from the tumor group only and a total of six genes including FOXM1, JUN, JARID2, BRE, BUB1B, and PHC2 were shown to significantly predict poor overall survival in log-rank tests in HCC." (PMID 37968735, 2023). "Besides, the expression of 7 genes (EZH2, FLT1, IRS1, KDR2, MYB2, JUN, and TIMP2) was significantly different in metastatic tissue when compared with the primary tumor." (PMID 36879084, 2023). "In total, five populations were designated tumour clusters, which had various features: (TumourC0) CD74 and APOD; (TumourC1) IF16, JUN and HSPA1A; (TumourC2) S100B and SCRG1; (TumourC3) NEAT1 and MALAT1; and (TumourC4) WFDC2 and RNASE1 (HLA‐DRA, CD68, CD3D, CD3E)." (PMID 37784253, 2023). "For example, the expression of genes such as JUN, FOS and DUSP1 showed an increasing pattern within the model and turned out to be high in both the tumor and normal samples, suggesting an involvement of these factors in tissue-specific differentiation processes." (PMID 37627150, 2023). "It was observed that JUN expression levels did not significantly correlate with tumor purity, but more likely affected prognosis by regulating the tumor microenvironment." (PMID 36091226, 2022). "According to a previous study, IL8 is involved in transcriptional regulation by activated NFκB,47 activating transcription factor 2 (ATF2), JUN, MAPK48 and other transcription factors; these transcription factors have also been reported to regulate tumour angiogenesis." (PMID 35224833, 2022). "Further importantly, the down-regulated expression of JUN, the inflammatory pathway activating gene in Y79 & WERI-Rb-1 cells suggests that inflammation plays a protective role against Rb tumor growth." (PMID 35359459, 2022). "Inhibitors targeting specific JNK-mediated downstream substrates and cellular events, such as phospho-c-JUN or the interaction of phospho-c-JUN binding partners, may show increased tumour specificity and efficacy." (PMID 36253406, 2022). "(G) LSCC tumours stained with c-MYC, c-JUN, and Δp63 antibodies." (PMID 34636321, 2021). "In those studies, normal and/or tumor tissues that underwent warm ischemia due to delayed processing after surgical incision demonstrated increased expression of FOS, FOSB, JUN, EGR1 as well as upregulation in immune system pathways compared to tissues processes immediately." (PMID 34814833, 2021). "Consequently, treatment of LSCC tumour cells with FT206 resulted in reduced c-MYC, c-JUN, Δp63, and USP28 protein levels, which were restored upon addition of MG132." (PMID 34636321, 2021). "USP28 inhibitor treatment resulted in a dramatic decrease in c-MYC, c-JUN, and Δp63 proteins levels and consequently induced substantial regression of autochthonous murine LSCC tumours and human LSCC xenografts, thereby phenocopying the effect observed by genetic deletion." (PMID 34636321, 2021). "The expression of JUN, CDK1, IRF1, and STAT1 was significantly higher in the RSI-Low tumours." (PMID 34078917, 2021). "Subsequently, through literature reviews about EGR1, JUN, and EZH2, we recognized that EGR1 and JUN could be tumor suppressors, whereas EZH2 can inhibit the expression of tumor suppressors." (PMID 34966410, 2021). "Furthermore, FRGs, IRGs, DEGs, and genes in the blue module were intersected, and seven hub genes (JUN, TNFAIP3, NOX4, HMOX1, SOCS1, CYBB, and TFRC), related to both ferroptosis and tumor immunity, were obtained." (PMID 35174170, 2021). "(C) Representative LADC and LSCC tumours stained with c-MYC, c-JUN, and Δp63 antibodies." (PMID 34636321, 2021). "Also, Δp63 and c-JUN, critical factors in squamous cell identity and tumour maintenance, respectively, showed higher protein levels in LSCC compared to LADC tumours." (PMID 34636321, 2021).
tumor (continued). "Interestingly, several HBV replication enhancers, for example, HLF and JUN appeared to be up-regulated in the PHH and the most differentiated HCC cells of the same tumor." (PMID 34290079, 2021). "RNA sequencing dataset analyses detected that AAL may regulate the expression of JUN, TLR4, and MYD88 to suppress tumor proliferation." (PMID 34337031, 2021). "The FOS protein family can bind with the JUN family (c-JUN, JUN B and JUN D) through a leucine zipper domain to form the transcription factor complex AP-1, which plays an important role in embryonic development, bone formation and tumor progression." (PMID 33456361, 2021). "RNA sequencing and TCGA dataset analyses detected that AAL may regulate the expression of JUN, TLR4, and MYD88 to suppress tumor proliferation." (PMID 34337031, 2021). "Furthermore, phosphorylation of the transcription factors MYC and JUN by DYRK2 is required for their degradation in the G1/S transition of the cell cycle, an event which is also tumor progression relevant." (PMID 33937075, 2021). "The current findings showed that JUN is not activated in all the tumor cells; only one cluster had this phenomenon." (PMID 34421602, 2021). "Furthermore, we find that EBV-miR-BART13-3p directly targets ABI2, known as a tumor suppressor and a cell migration inhibitor, drives epithelial-mesenchymal transition (EMT) by activating c-JUN/SLUG signaling pathway." (PMID 31907338, 2020). "EYA4 overexpression suppressed the expression levels of c‐JUN and VEGFA in HCC tumours." (PMID 30957411, 2019). "We predicted that JUN can regulate mononuclear cells to release VEGFA, which may promote tumor angiogenesis, which was proved as the reason for tumor initiation and progression." (PMID 31531018, 2019). "Both JUN and SPP1 are genes known to promote cancer cell invasiveness and tumor metastasis." (PMID 30459815, 2018). "The genetic network connecting JUN and MAPK signaling may explain why KRAS mutant tumor cells are traditionally seen as highly refractory to MEK inhibitor therapy, but these genetic interactions may also provide a therapeutically exploitable vulnerability." (PMID 30482246, 2018). "It is also unclear how the increase in KLF6 and JUN gene products in response to hypoxia influences cancer phenotypes, as KLF6 and JUN are known to act as oncogenes or tumor suppressors depending on various factors, such as cell type and stimuli derived from different cellular environments." (PMID 26703734, 2015). "JUN is itself a proto-oncogene, and increased IIS occurs in many diverse tumor types." (PMID 25085992, 2014). "Thus, in the normal mammary epithelium these RTKs are repressed or expressed at a low level and their signaling is primarily oriented toward the JUN/MAPK pathway, whereas when upregulated in tumor cells they stimulate the PI3K/AKT pathway." (PMID 23805779, 2013). "At the level of the tumor-initiating cell, the PI3K/AKT pathway could stimulate self-renewal and/or proliferation and the JUN/MAPK pathway cell differentiation or cell cycle arrest." (PMID 23805779, 2013). "The three genes that were significant for ‘Time’, ‘T2’ and the ‘T3’ contrasts in the Tumor samples (JUN, FOSB and ABL1) were selected for technical validation with Real Time PCR (RT-PCR) analysis in the same Tumor tissues belonging to the 14 different patients analyzed by microarrays." (PMID 23308215, 2013). "The downstream effects of the activated PI3K/AKT and inhibited JUN/MAPK pathways are multiple, but at least two could be of primary importance for the behavior of the tumor-initiating cell that fuels the tumor growth." (PMID 23805779, 2013). "However, only c-JUN and AL050002 correlated with tumor stage by qRT-PCR and only AL050002 gene correlated with B3 histology; in the current study, expressed above background noise of the array (data not shown)." (PMID 22912720, 2012).
tumor (continued). "In addition, abnormal tumor TNF pathways mediated by abnormal expressions of TNF, NF-κB, FOS, JUN, and JUNB were observed, and scATAC-seq results confirmed the presence of abnormal accessibility binding sites for the transcription factors FOS, JUN, and JUNB." (PMID 38770048, 2024). "The tumor-subtype and stage-dependent expression of JUN was highly significant when comparing healthy and primary (p = 2.8e-05), primary and metastatic CRPC (p = 2.6e-43) and primary and metastatic NEPC (p = 5.3e-04), suggesting JUN as a potential marker of progressive subtypes of PCa." (PMID 38811984, 2024). "Interestingly, mRNA levels of JUN were not significantly different between normal and tumor samples." (PMID 38023989, 2023). "Moreover, analyses of SOX10– and SOX10+MITF– tumors developed in NSG mice at molecular level suggested a profound difference between the tumor types and reflected the tumor growth difference and sustained increased expression of NGFR, JUN, and WNT5A in the SOX10+MITF– melanoma tumors." (PMID 36040798, 2022). "However, the current data demonstrated that JUN is activated in some cell clusters and undergoing anaerobic metabolism in tumor tissues without sorafenib." (PMID 34421602, 2021). "In addition to canonical NF-κB pathways, STAT1, STAT3, JUN, EGFR, and CEBPB were also on the top list, and these proteins may play crucial roles in tumour-induced DC signal transduction." (PMID 28350008, 2017). "The activation of three stringent UPRs related to DNA damage pathways in both GL261 and LLC tumors (CHUK/IKBKA, IKBKB and JUN) or in all three tumor models (CHUK, IKBKB) may reflect the cytotoxic responses common to CPA treatment in all three tumor models." (PMID 27515027, 2016). "Moreover, they showed that miR-1285-3p could directly repress expression of JUN oncogene in HCC cells, indicating a potential tumor suppressor role of miR-1285-3p." (PMID 27517633, 2016). "In addition, JUN knockdown by shRNAs reduced cell viability in vitro and inhibited tumor formation in vivo without an observable effect on the differentiation state of the LPS cells." (PMID 25888633, 2015). "In this article, we now elucidate a negative feedback mechanism in which high YAP activity is restrained by the recruitment of JUN/NCOR1 repressor complexes and show that this non-canonical JUN function is part of a tumor suppressor mechanism in the liver." (PMID 39210147, 2024). "Tumor cells with fused genes showed overexpression of FOSB, FOS, and JUN, while tumor cells without fused genes overexpressed CXCR6 and DUSP4." (PMID 37736898, 2023). "In five cases, the finding of similar 12q amplicons, but without concomitant JUN amplification or genome-wide CN changes, was interpreted to suggest ALT or WDLS, depending on the location of the tumor." (PMID 35318454, 2022). "Irrespective of oncogenic driver, tumour cells upregulate USP28, which stabilizes proto‐oncogenes, such as c‐MYC, c‐JUN or NOTCH." (PMID 35364627, 2022). "The results show that the phosphorylation of p-MEK and the expression of MYC, JUN and PDCD6 were higher in tumor tissues than in adjacent normal tissues." (PMID 32746883, 2020). "It is noteworthy that the USP28 targets c‐JUN and c‐MYC were not downregulated in established tumours in KPLU mice, when compared to KPL." (PMID 32128997, 2020).
cancer (698 papers, 2005 to 2026). A tumor composed of atypical neoplastic, often pleomorphic cells that invade other tissues. "JUN is a gene that encodes a protein associated with diseases such as various malignant tumors 11-14." (PMID 40092686, 2025). "Through systematic analysis of nine high‐risk contaminants, we identified pan‐cancer targets and key pathway modules, with subsequent validation of hub genes (JUN, CDC42, MAPK14) in breast, colon, and prostate cancers using TCGA datasets." (PMID 41246859, 2025). "An example is the c-Jun Proto-Oncogene (JUN) family of transcription factors, which has been implicated in driving fibrogenesis and cancer." (PMID 40142664, 2025). "Previous studies have implicated IGFBP5 in cancer inhibition by temporally inactivating the insulin-like growth factor receptor, and JUN has been linked to increased tamoxifen sensitivity through protein kinase C activation." (PMID 38791962, 2024). "JUN, a well-studied member of the AP-1 transcription factor family, is implicated in various cellular processes, including cancer, survival, apoptosis, proliferation, and tissue development." (PMID 39295929, 2024). "For JUN, a proto-oncogene, it is highly susceptible to loss and translocation during malignant tumor development." (PMID 38306566, 2024). "The locus of JUN is located in the chromosomal region closely associated with human malignant tumors, and JUN is involved in various biological activities including cell growth, proliferation and apoptosis." (PMID 36641437, 2023). "JUN is a proto-oncogene transcription factor and regulates transcription-caused cancer formation (Expression of JUN in cancer - Summary - The Human Protein Atlas, 2021)." (PMID 37671046, 2023). "c-Jun encoded by gene JUN is one of the important cancer-related transcription factors and is a key molecule in glucose metabolism and cancer metastasis." (PMID 36476606, 2022). "JUN encodes for the c-Jun transcription factor subunit of the AP-1 complex that participates in inflammatory responses to several types of cancer." (PMID 34869521, 2021). "Elevated c-JUN/SLUG signaling has been found in multiple cancer types and shows a significant association with invasion and metastasis." (PMID 31907338, 2020). "Activated JUN encodes a jun proto-oncogene, an AP-1 transcription factor subunit, which is associated with cancer cell proliferation and angiogenesis." (PMID 32256671, 2020). "c-JUN has been previously implicated in the progression of BC showing an increase in invasive potential of the cancer cells that is associated with angiogenesis and proliferation." (PMID 29100386, 2017). "Genes associated with cancer development were also significantly increased including JUN, FOS and M2 macrophage markers." (PMID 26448646, 2015). "Downregulation of transcription factors such as JUN has been observed in advanced stages of other cancers and its loss of activity has been postulated to be involved in this transition." (PMID 17430594, 2007). "Thus, patients’ cancers exhibited high expression levels of PTGS2/ESR2/EGFR/JUN/MMP2 genes’ signatures are associated with poor prognosis." (PMID 39707884, 2024). "As JUN has been associated with several types of cancer, we hypothesized that it might be involved in T4O-induced biological functions." (PMID 37375197, 2023). "JUN (JUN proto-oncogene protein, AP-1 transcription factor) is related to immune infiltration, which causes inflammation and cell death through immunosuppression, leading to cancer." (PMID 36639776, 2023). "Studies have shown the association between transcription factor JUN and drug resistance in several cancer types; moreover, JUN could interact with the microenvironment, thus regulating inflammation and immunity." (PMID 36672292, 2023).
cancer (continued). "JUN is a transcription factor that plays a key role in controlling cell proliferation, apoptosis and differentiation, whose amplification has been associated with cancer progression and growth and with the increase in invasive properties." (PMID 36672146, 2023). "The identification of three functional states associated with c-JUN N-terminal phosphorylation may have implications for the development of novel therapeutic cancer strategies." (PMID 36253406, 2022). "The proto-oncogene JUN is associated with the cis-regulatory lncRNA RP4-794H19.1 and is very commonly found in cancers; JUN has been linked to the TNF signaling pathway, and may be a vital gene in NPC." (PMID 32863767, 2020). "Furthermore, targeting c-JUN and its associated pathways may open up new avenues for therapeutic interventions in various diseases, including cancer and regenerative medicine." (PMID 39876710, 2025). "Moreover, we found a well-recognized oncogene, JUN, affected by archaic introgression in the Zhuang population, which could be responsible for the present-day differential prevalence and association with cancers for the JUN variants." (PMID 37316654, 2023). "JUN is a multifaceted TF as a component of the transcription factor AP‐1 complex whose function is associated with embryonic development, tissue‐specific development, such as neuron, blood and bone, T cell differentiation and activation, and cancer cell survival and proliferation." (PMID 34459128, 2021). "We conducted ectopic overexpression experiments to elevate the levels of GPX3 and JUN in cancer cells." (PMID 40092686, 2025). "In this comparison, the CREB1, FOS, HSPA5, and JUN genes exhibited a significant downregulation in malignant tumors compared to group 1 (p < 0.05) (Analysis 1)." (PMID 40722651, 2025). "In this analysis, the JUN gene in OC was present in the TNF signaling pathway indicating its relation with cell proliferation across various cancers." (PMID 41186627, 2025). "Subsequent functional experiments with NSCLC cell lines and organoids validated that mannose can inhibit cancer cell growth by targeting the OGT/hnRNP R/JUN/IL-8 axis." (PMID 39990658, 2025). "The results demonstrate that ITGB1 and its target genes FOS/JUN were commonly expressed in all four cancer types, indicating their potential as pan-cancer therapeutic targets." (PMID 40725477, 2025). "Yin and colleagues stratified BC patients into high and low risk cancers based on a seven gene expression assay (BATF, CD3D, HLA-DQB2, JUN, MAP2K6, NFKBIE, PAK1)." (PMID 40148963, 2025). "Hsa-miR-744, which regulates SERPINA1 and JUN, has been found to be elevated in various cancers, with significant implications for prognosis." (PMID 39893248, 2025). "FOXC1 and JUN assumed critical roles in promoting cancer proliferation, metastasis, and chemoresistance." (PMID 38672263, 2024). "Expression of JUN was increased in surviving cells in both cell lines suggesting a possible targetable subunit across cancers." (PMID 38385626, 2024). "For example, JUN was recently shown to be sensitive to RocA, an anti-cancer drug that clamps eIF4A onto specific polypurine sequences in the 5′ UTRs of a subset of mRNAs." (PMID 38483896, 2024). "At the beginning of the JUN gene coding region, higher CVs on the start codons were observed in nine types of cancer tissues." (PMID 38970366, 2024). "Recently, it was shown that components of the AP-1 transcription factor (FOS, FOSB, JUN), EGR1, and NR4A1 behave as a conserved co-regulated group of genes whose expression is associated with ZFP36 in cancer cells." (PMID 39026155, 2024). "The expression of EGR1 and JUN influences cancer progression by regulating cell cycle processes and promoting cell proliferation." (PMID 38872167, 2024).